CCN1 (cellular communication network factor 1)
Description:
Promotes cell proliferation, chemotaxis, angiogenesis and cell adhesion. Appears to play a role in wound healing by up-regulating, in skin fibroblasts, the expression of a number of genes involved in angiogenesis, inflammation and matrix remodeling including VEGA-A, VEGA-C, MMP1, MMP3, TIMP1, uPA, PAI-1 and integrins alpha-3 and alpha-5. CCN1-mediated gene regulation is dependent on heparin-binding. Down-regulates the expression of alpha-1 and alpha-2 subunits of collagen type-1. Promotes cell adhesion and adhesive signaling through integrin alpha-6/beta-1, cell migration through integrin alpha-v/beta-5 and cell proliferation through integrin alpha-v/beta-3.
Synonyms: IBP-10; IGFBP-10; CYR61; GIG1; IGFBP10
Tractability: Small molecule: a structure with a bound ligand is known. Antibody: UniProt places it where antibodies can reach, with medium confidence; UniProt predicts a signal peptide or a membrane-spanning region; its Gene Ontology location is reachable by antibodies, with medium confidence. PROTAC: ubiquitination databases record sites on it.
Gene: Protein-coding gene on chromosome 1 (85,580,756 to 85,584,589, forward strand). Ensembl gene ENSG00000142871.
Subcellular location: Secreted
Pathways (Reactome):
Metabolism of proteins: Post-translational protein phosphorylation; Regulation of Insulin-like Growth Factor (IGF) transport and uptake by Insulin-like Growth Factor Binding Proteins (IGFBPs)
Gene Ontology:
Molecular function: protein binding; extracellular matrix structural constituent; heparin binding; integrin binding; extracellular matrix binding
Biological process: integrin-mediated signaling pathway; positive regulation of BMP signaling pathway; positive regulation of bone mineralization; positive regulation of cell migration; positive regulation of osteoblast differentiation; positive regulation of osteoblast proliferation; positive regulation of transcription by RNA polymerase II; regulation of ERK1 and ERK2 cascade; cell adhesion; positive regulation of cell differentiation; signal transduction; positive regulation of developmental process; positive regulation of ossification; regulation of multicellular organismal development
Cellular component: extracellular matrix; non-collagenous component of interstitial matrix; endoplasmic reticulum lumen; extracellular region
Genetic constraint (gnomAD): Loss-of-function variants: 12 observed, 38.22 expected, observed/expected ratio (o/e) 0.31, 90% interval 0.2 to 0.51. The upper end of that interval is the gene's LOEUF score, 0.51, which puts it in group 2 of 6, group 1 being the genes least tolerant of losing a copy. Missense variants: 466 observed, 510.27 expected, observed/expected ratio (o/e) 0.91, 90% interval 0.85 to 0.99. Synonymous variants: 202 observed, 203.79 expected, observed/expected ratio (o/e) 0.99, 90% interval 0.88 to 1.11.
Homologues: Orthologues: chimpanzee CCN1 (99% identical), macaque CCN1 (98% identical), dog CCN1 (94% identical), guinea pig CCN1 (94% identical), rabbit CCN1 (93% identical), mouse Ccn1 (92% identical), rat Ccn1 (92% identical), pig CCN1 (90% identical), tropical clawed frog ccn1 (79% identical), zebrafish ccn1 (65% identical). Paralogues in human: CCN2 (44% identical), CCN3 (39% identical), CCN4 (36% identical), CCN6 (32% identical), CCN5 (26% identical).
Diseases named in the same sentence as CCN1 in open-access papers:
CCN1 is named in the same sentence as 286 diseases in open-access papers, as found by Europe PMC text mining. Sharing a sentence is not in itself a finding about the gene and the disease. The quoted sentences say what the papers report.
breast cancer (109 papers, 2005 to 2025). A primary or metastatic malignant neoplasm involving the breast. "Elevated CCN1/CYR61 levels is associated with poor prognosis for various cancers including breast cancer, prostate cancer, gastric cancer, oral squamous cell carcinoma, lung cancer, and hepatocellular carcinoma." (PMID 41012700, 2025). "Overexpression of CCN1 in breast cancer cells is found to be associated with increased tumor size and vascularization." (PMID 34940056, 2021). "The elevated level of CCN1 is associated with lymph node metastases and a worse chance of recovery in breast cancer patients." (PMID 34940056, 2021). "CCN1 expression strongly correlates with known markers for invasiveness, and associates with the ability of breast cancer cells to invade in vitro and metastasize in vivo." (PMID 27713913, 2016). "CCN1 overexpression is associated with the progression of various tumors, including prostate cancer, breast cancer, glioma, colorectal cancer, and osteosarcoma, through its ability to promote angiogenesis, cell migration or proliferation." (PMID 27167338, 2016). "High CCN1/CCN3 or CCN2/CCN3 mRNA ratios were found to be associated with a highly metastatic phenotype in breast cancer cells." (PMID 22427255, 2012). "We first employed site-specific CCN1 mutations specifically abolishing the receptor-binding sites to either αvβ3/αvβ5 or α6β1 to delineate the integrin partner responsible for CCN1-driven endocrine resistance in breast cancer." (PMID 35148282, 2022). "Furthermore, zoledronic acid suppresses breast cancer growth through inhibition of the AKT/forkhead box protein O3a (FOXO3a)-mediated expression of the extracellular matrix-associated protein CCN family member 1 (CCN1)." (PMID 34064589, 2021). "As visualized in the analysis, CCN1, CCN2 and EDN1 were among the most robustly downregulated genes, and it is notable that all of these genes have been implicated in breast cancer development." (PMID 41145489, 2025). "CCN1 expression levels correlate with invasiveness and overall aggressiveness in metastatic triple-negative and basal-like breast cancer cell types." (PMID 41012700, 2025). "High expression of CCN1 has been detected in various cancers such as breast cancer, gastric cancer, and ovarian cancer." (PMID 40234387, 2025). "LPA and TGF-β1 signaling have been reported to regulate CCN1 in breast cancer and prostate epithelial cells." (PMID 39273316, 2024). "In the present study, we used previous mutational analyses showing that distinct integrin-binding sites of CCN1 can function independently of one another to determine the signaling pathway through which CCN1 mediates endocrine resistance in breast cancer." (PMID 35148282, 2022). "Our own previous studies and those of others have established a significant correlation between elevated levels of CCN1 and more advanced disease and metastatic phenotypes in in vitro breast cancer models and in patients." (PMID 35148282, 2022). "In this context, a recent study has highlighted a role for CCN1 in the development of endocrine resistance in patients with breast cancer, identifying it as a potential therapeutic target to overcome refractoriness to a wide-range of antiestrogen therapies." (PMID 35148282, 2022). "Accordingly, MCF-7/pBABE, MCF-7/CCN1, MCF-7/D125A-CCN1, and MCF-7/TM-CCN1 cells all exhibited a mass-like morphology with disorganized nuclei and filled colony centers characteristic of luminal-like breast cancer cells." (PMID 35148282, 2022). "CCN1/CYR61 promotes angiogenesis, tumor growth and chemoresistance by binding to its integrin receptor αvβ3 in endothelial and breast cancer (BC) cells." (PMID 35148282, 2022). "Forced CCN1 expression in MCF7 low-invasive breast cancer cell line increases its ability to adhere to collagen and fibronectin, invasiveness on fibronectin substrate and migratory ability." (PMID 34228239, 2021).
breast cancer (continued). "Paradoxically, therapeutic measures have also been developed to inhibit breast cancer development targeting CCN1." (PMID 34940056, 2021). "CCN1 is a well-established prognostic factor for breast cancer, especially for Triple Negative Breast Cancer (TNBC)." (PMID 34940056, 2021). "By injecting the cancer cell to the mice model, the authors observed that constitutive CCN1 silencing decreased breast cancer lung metastasis." (PMID 33105556, 2020). "Next, we assessed that a link between CCN1 and tumor stiffness exists in vivo using the orthotopically transplanted mouse E0771 breast cancer cell model." (PMID 28694244, 2017). "In a model of lung metastasis where MDA‐MB‐231 breast cancer cells are intravenously injected, CCN1 depletion in the cancer cells inhibited metastasis by reducing extravasation to the lung and enhancing cancer cell anoikis." (PMID 28694244, 2017). "Estrogendependent MCF-7 breast cancer cells, which naturally express very low to undetectable levels of CCN1, were transfected with full-length CCN1 cDNA and stable cell clones were selected with zeocin." (PMID 27713913, 2016). "In this work, we aimed to examine the influence of the metastasis inducer CCN1 on the expression of cancer cell-associated FASN as well as the role of FASN activity on some of the key metastatic features acquired by CCN1-overexpressing breast cancer cells." (PMID 27713913, 2016). "CCN1 plays unique roles in different tumor types: it is an oncogenic factor for cancers of the breast, prostate, and stomach as well as for glioma, esophageal squamous cell carcinoma, and chondrosarcoma." (PMID 25187756, 2014). "In the case of breast cancer, alternative splicing of intron 3 in CCN1 pre-mRNA is regulated by hypoxia and acidosis which further leads to disease progression." (PMID 24965524, 2014). "This extends previous findings of intron splicing with regard only to intron 3 in CCN1 mRNA of breast cancer cells." (PMID 24965524, 2014). "In contrast, CCN1 inhibits apoptosis induced by anti-cancer drugs in breast cancer cells and in ovarian carcinoma cells." (PMID 25187756, 2014). "Previous studies have reported similar nuclear localization of CCN proteins in cancer cells, including nuclear localization of CCN1 in prostate carcinoma and breast cancer cells and the nuclear localization of CCN2 in melanoma cells." (PMID 25541962, 2014). "CCN1 has been shown to regulate breast cancer proliferation and survival by participating in a positive CCN1-αvβ3 autocrine loop; CCN1 stimulates the activation of ERK1/2-MAPK, which increases the expression of integrin αvβ3 expression." (PMID 22481923, 2012). "Elevation of CCN1 has been found in breast cancer, pancreatic cancer, and gliomas, while in endometrial cancer and lung carcinoma, CCN1 level is decreased." (PMID 22701179, 2012). "We hypothesize that CCN1 protein can be used as a soluble marker for the early detection of breast cancer in a multi-cancer detection (MCD) platform." (PMID 41012700, 2025). "Moreover, YAP, CCN2 (CTGF) and CCN1 (Cyr61) were also found to be overexpressed in tamoxifen-resistant breast cancer and induced transcriptional repression of ERα." (PMID 40157909, 2025). "Recent trials assessing CCN1 plasma concentrations in breast and lung cancer patients, compared to healthy control populations, have shown elevated expression levels at the earliest stages of breast cancer development." (PMID 41012700, 2025). "Notably, cellular communication network factor 1 (CCN1) signaling, through α6β1 integrin, promotes an endocrine‐resistant phenotype, potentially through the direct binding of CCN1 to ERα, thus regulating transcriptional events in ERα+ breast cancer cells." (PMID 39285617, 2025). "Increased expression of CCN1 might promote angiogenesis, deregulated proliferation, enhanced cell survival and tumor invasiveness, and chemoresistance in breast cancer cells by activating integrin αvβ3-driven cellular signaling." (PMID 35148282, 2022).
breast cancer (continued). "We next assessed whether modulation of CCN1 expression and/or specific modification of CCN1-integrin(s) binding would affect the anti-estrogen sensitivity of ER-positive breast cancer cells." (PMID 35148282, 2022). "These demonstrated that circulating protein CCN1 could be applied in the early detection of breast cancer, and it was suggested it could be, thus, included in liquid biopsy panels containing other DNA or proteins." (PMID 35565189, 2022). "We assessed whether specific modification of CCN1-integrin(s) binding would impact the ability of CCN1 to modulate estrogen dependency of ER-positive breast cancer cells." (PMID 35148282, 2022). "In vitro studies have also clarified the ability of CCN1 to overcome estrogen dependency and elicit resistance to the selective estrogen receptor (ER) modulators and down-regulators (SERMs/SERDs) tamoxifen and fulvestrant in ER-positive breast cancer cells." (PMID 35148282, 2022). "CCN1 is currently known as one of the potential targets for chemotherapy against breast cancers." (PMID 34940056, 2021). "Cyr61 (CCN1) is an integrin receptor and an angiogenesis inducer in breast cancer." (PMID 34940056, 2021). "Their study also indicated the CCN1-β1 integrin–AMPKα axis may play a role in breast cancer metastasis to the lung." (PMID 33105556, 2020). "In agreement with earlier reports on the up-regulatory effects of androgens, progestins, growth factors, growth factor receptors, and hypoxia on FASN gene activity, CCN1- stimulated FASN expression seems to involve activation of the SREBP pathway in breast cancer cells." (PMID 27713913, 2016). "Because estrogen independence and progression to a metastatic phenotype are hallmarks of therapeutic resistance and mortality in breast cancer, this previously unrecognized CCN1-driven lipogenic phenotype represents a novel metabolic target to clinically manage metastatic disease progression." (PMID 27713913, 2016). "CCN1 is overexpressed in about 30% of triplenegative breast carcinomas (TNBC)." (PMID 27713913, 2016). "Cysteine-rich protein 61 (CCN1/Cyr61) has been used as an important mediator in proliferation and metastasis of breast cancer; blockage of Cyr61 might be a potent target for breast cancer treatment." (PMID 25048831, 2015). "Moreover, the anti-human CCN1 antibody, denoted as 093G9, was shown to inhibit breast cancer cell migration and invasion through upregulation of the MMP inhibitors TIMP1 and TIMP2." (PMID 24551846, 2014). "CCN1 has been shown to act both as an oncogene, e.g. in mammary cancer, and as a tumor suppressor." (PMID 24965524, 2014). "In addition, studies have also shown that patients with elevated expression of CCN1 in their breast cancer have a worse prognosis." (PMID 25062088, 2014). "CCN1 has also been recommended as a candidate target for breast cancer bone metastases." (PMID 24551846, 2014). "ERK is regulated by CCN1 in breast cancer and during osteoblast differentiation." (PMID 25187756, 2014). "Because αvβ3-dependent activation of the MAPK pathway was previously found to drive CCN1-directed cell survival and chemoresistance, we explored whether specific modulation of the CCN1-integrin(s) binding differentially altered ERK1/ERK2 activity in breast cancer cells." (PMID 35148282, 2022). "Importantly, CCN1 has been involved in breast cancer progression." (PMID 35565189, 2022). "Whereas CCN1 overexpression-driven estrogen independence and progression to a metastatic phenotype are hallmarks of therapeutic resistance and mortality in breast cancer, the precise mechanisms by which CCN1 promotes more aggressive breast cancer metastatic phenotypes remain unknown." (PMID 27713913, 2016). "Additionally, the related molecule, CCN1 (also known as CYR61) promotes anti-apoptotic pathways when over-expressed in breast cancer MCF7 cells in an integrin-dependent manner, consistent with the recognition of integrins as signaling receptors for CCN proteins." (PMID 16303051, 2005).
breast cancer (continued). "Indeed, we noted that treatment of breast cancer cells with tryptase affected the chromatin accessibility in several regions, including reduced chromatin accessibility in regions containing genes whose transcription were suppressed by tryptase (e.g., CCN1, CCN2)." (PMID 41145489, 2025). "CCN1 and CCN2 are up regulated in breast cancer and their expression correlates with staging and local (CCN1) or bone (CCN2) invasiveness." (PMID 34228239, 2021). "In contrast with the prometastatic role of CCN1 and CCN2, CCN6 acts as an oncosuppressor in breast cancer, preserving epithelial differentiation." (PMID 34228239, 2021). "While the expression of CCN proteins varies in different cancer types, CCN1, CCN2, CCN3 and CCN4 participate in tumor development and act as oncogenes, but CCN1, CCN3, CCN5, and CCN6 inhibit tumor growth and play tumor-suppressive roles in breast carcinomas." (PMID 34940056, 2021). "In MCF-7 and MDA-MB-231 human breast cancer cell lines, both LPA and EGF stimulated proliferation, Erk activation, Akt activation, and CCN1 induction." (PMID 26821052, 2016). "In the present study, we show that CCN1 significantly stimulates FASN gene transcription and FASN protein accumulation in breast cancer cells." (PMID 27713913, 2016). "The activities of Itgb1 (coding for integrin β1), TGFβ2 and Vegfα are mediated, at least in part, by Cyr61 (CCN1,)–a secreted matrix protein involved in the clinical progression of breast cancer to an invasive phenotype." (PMID 19450255, 2009). "CCN1, CCN2 and CCN4 are expressed at elevated levels in advanced breast cancers; increased CCN1 levels are thought to lead to more invasive breast cancers." (PMID 18789696, 2008). "We show that a single amino acid mutation in the αvβ3 binding site within a 20-amino acid sequence (V2) in CCN1 failed to suppress the endocrine resistance phenotype induced by overexpressing the wild-type form of CCN1 in ER-positive MCF-7 breast cancer cells." (PMID 35148282, 2022). "The pro-tumorigenic CCN1, CCN2, CCN3, and CCN4 may lead to human breast cancer, although the anti-tumorigenic actions of CCN5 and CCN6 are also present." (PMID 34940056, 2021). "CCN1, CCN3, CCN5, CCN6 play a critical role in survival in breast cancer." (PMID 34940056, 2021). "CCN1, CCN3, CCN5 and CCN6 may play dual roles; their expression can inhibit breast cancer growth, and their absence can induce carcinoma." (PMID 34940056, 2021). "CCN1, CCN2, CCN3, and CCN4 are pro-tumorigenic and may be responsible for human breast carcinoma; while CCN1, CCN3, CCN5 and CCN6 have anti-tumorigenic effects." (PMID 34940056, 2021). "Immunoblotting procedures confirmed the ability of U0126 and LY294002 to dose-dependently decrease FASN protein expression in CCN1-overexpressing breast cancer cells (data not shown)." (PMID 27713913, 2016). "This is in contrast to our findings in which we observed high CCN3 levels in the context of low CCN1 and CCN2 expression in bone metastatic breast cancer cells and also contrasts with the observation that human breast cancer bone metastases that display high CCN3 mRNA expression." (PMID 22427255, 2012). "However, designing treatment strategies based on breast cancer subtype and CCN1 status have not been thoroughly studied." (PMID 41012700, 2025). "Because an increase in PI uptake can be viewed as a reliable indicator of cell injury severity, our results suggest that pharmacological blockade of FASN activity causes significantly increased amounts of cellular damage in CCN1-overexpressing when compared with CCN1-negative breast cancer cells." (PMID 27713913, 2016). "We show that CCN1/CYR61 signaling via α6β1, but not via αvβ3/αvβ5, drives an endocrine resistance phenotype that involves the unforeseen direct binding of CCN1 to ERα to regulate its transcriptional activity in breast cancer cells." (PMID 35148282, 2022).